PCBP2-OT1 (PCBP2 overlapping transcript 1)
Synonyms: TUC338; uc.338; TUC.338
Gene: Long non-coding RNA gene on chromosome 12 (53,464,468 to 53,465,057, forward strand). Ensembl gene ENSG00000282977.
Diseases named in the same sentence as PCBP2-OT1 in open-access papers:
PCBP2-OT1 is named in the same sentence as 10 diseases in open-access papers, as found by Europe PMC text mining. Sharing a sentence is not in itself a finding about the gene and the disease.
PCBP2-OT1 shares sentences with these, for which no sentence is quoted: bladder cancer (2 papers); cancer (2); lung carcinoma (2); diffuse large B-cell lymphoma (1); hepatocellular carcinoma (1); laryngeal squamous cell carcinoma (1); liver cancer (1); oral squamous cell carcinoma (1); pancreatic cancer (1); tumor (1).